CRP (C-reactive protein)
Diseases named in the same sentence as CRP in open-access papers (continued):
Sharing a sentence is not in itself a finding about the gene and the disease.
COVID-19 (continued). "Furthermore, patients with COVID-19 experience elevated levels of serologic indicators of inflammation, such as C-reactive protein (CRP), erythrocyte sedimentation rate (ESR), lactate dehydrogenase (LDH), and procalcitonin." (PMID 34745112, 2021). "The PAB level was inversely correlated with C-reactive protein for COVID-19 patients." (PMID 34242179, 2021). "Since cCLP has been suggested as a reliable biomarker of inflammation in several diseases, we first tested the correlation with two parameters frequently increased in most of COVID-19 longitudinal studies, like CRP and fibrinogen (FBG) by means of Pearson’s test." (PMID 33956194, 2021). "The findings of our study have significant clinical implications in that elevated CRP values during admission could be a sign of subsequent worse prognosis in patients with COVID-19 and pre-existing CVD." (PMID 34300252, 2021). "Meanwhile CRP can be used an adjunct biomarker for COVID-19 detection." (PMID 34205852, 2021). "LDH and CRP have been suggested as surrogates of COVID-19 severity." (PMID 33655804, 2021). "In the early stages of COVID-19, CRP levels were positively correlated with lung lesions and could reflect disease severity." (PMID 33995382, 2021). "Likewise, the CRP-to-albumin ratio (CAR) can predict mortality in COVID-19 patients with an AUROC of 0.807." (PMID 34683480, 2021). "In multivariate analysis, CRP (odds ratio [OR]: 1.103; 95% confidence interval [CI]: 1.060–1.148; p < 0.001) and total bilirubin (OR: 1.612; 95% CI: 1.330–1.954; p < 0.001) levels were independent predictors of myocarditis in COVID-19." (PMID 34928467, 2021). "Disease severity was also associated with the basal levels of laboratory markers known to be associated with COVID-19-related complications, such as lactate dehydrogenase (LDH; p = 0.017), D-dimer (p = 0.004), troponin T (p < 0.001) or C-reactive protein (CRP; p = 0.039)." (PMID 34868021, 2021). "Likewise, higher levels of CCL2, CCL7, CCL20, and CXCL10 were associated with lower blood lymphocyte count and higher inflammatory markers (CRP and ferritin), which are clinical markers of severe disease and poorer outcome in COVID-19." (PMID 33704068, 2021). "Indeed, in hospitalized patients, CRP has prognostic value, even in moderately affected COVID-19 patients." (PMID 35011944, 2021). "CRP and lymphocyte count were found to be early warning signs of COVID-19 mortality." (PMID 33996864, 2021). "Hospitalized COVID-19 patients demonstrated statistically significantly higher concentrations of CRP (48 [9.0–81.0] vs. 1.9 [1.0–5.5], p < 0.001) and creatinine (91.8 [85.5–97.2] vs. 71.0 [61.0–80.0], p = 0.022) and lower albumin (39.1 [37.7–42.1] vs. 44.0 [42.0–46.0], p = 0.010)." (PMID 34943125, 2021). "Moreover, high WBC, CRP, LDH, D-dimer, low corrected calcium and need for NIV are parameters significantly associated with severe COVID-19." (PMID 35076497, 2021). "This is the first report on CRP apheresis in an early COVID-19 patient with fulminant CRP increase." (PMID 34408751, 2021). "Similarly, high CRP levels corelates with the severity of COVID-19, ARDS, myocardial damage, and mortality." (PMID 34616572, 2021). "Recognized biomarkers in COVID-19 and other respiratory infections such as neutrophil count, C-reactive protein, D-dimer, creatinine, and urea in the blood, can distinguish SARS-CoV-2 infected from non-infected patients and are further increased in more severe patients." (PMID 34685377, 2021). "A randomized clinical trial using CRP apheresis in early-phase COVID-19 patients is planned." (PMID 34408751, 2021). "Among the altered hematological parameters, elevated CRP and ferritin levels might use as predictable markers to assess the COVID-19 severity and mortality risks." (PMID 34314447, 2021). "It is suggested that CRP level calibration can be a useful tool in managing COVID-19 patients." (PMID 35154611, 2021).
COVID-19 (continued). "As is the case with COVID-19, there is an increase in IL-1β, IL-6, and C-reactive protein (CRP)." (PMID 34367545, 2021). "However, IL-6 levels along with other laboratory indicators, like CRP, prothrombin time (PT), and D-dimer, provide a more accurate assessment of complications in COVID-19 patients." (PMID 35126355, 2021). "To date, several clinical and biochemical parameters have been used to predict the severity of COVID-19, including the following: C-reactive protein (CRP), serum amyloid A (SAA), interleukin (IL)-6, lactate dehydrogenase (LDH), white blood cell count, d-dimer, cardiac troponin and platelet count." (PMID 34667241, 2021). "So far, there is no pharmaceutical option to reduce the extremely high synthesis/level of CRP during an acute phase response, but the rapid reduction of high CRP levels in medium and severe courses of COVID-19 was proposed early on during the pandemic and also recently." (PMID 34408751, 2021). "Additionally, the high C-reactive protein (CRP), serum ferritin, lactate dehydrogenase (LDH), and several other immunological markers were associated with an increased risk of COVID-19 and death." (PMID 34776007, 2021). "Laboratory data have demonstrated a lower erythrocyte count, hematocrit volume, hemoglobin level, lymphocyte count, leukocyte count, and albumin level, but an increase in aspartate aminotransferase, alanine aminotransferase, and C-reactive protein (CRP) levels in the mild COVID-19 cases." (PMID 33869282, 2021). "Infammatory markers such as CRP and PCT were associated with the COVID-19 severity." (PMID 34222268, 2021). "Another study identified increased CRP levels in a limited number (31.0%) of COVID-19 patients." (PMID 33693030, 2021). "Although high-sensitivity C-reactive protein level is a known factor for COVID-19 severity and prognosis, we showed that it could also differentiate patients with COVID-19 from patients with non-COVID viral pneumonia and healthy individuals." (PMID 33404516, 2021). "CRP and bedside vital signs were the strongest predictors of COVID-19 severity." (PMID 33815405, 2021). "In COVID-19, it has been reported that CRP levels can be used for early identification of pneumonia and the assessment of severe pulmonary infectious diseases, even though the exact effect remains unclear." (PMID 33854695, 2021). "In severe COVID-19 cases, laboratory parameters such as hematological findings, coagulation tests, liver function tests, D-dimer, ferritin, and acute phase reactants such as CRP show marked alterations, which are suggestive of a cytokine storm." (PMID 34590796, 2021). "have indicated the optimal cut-off point of CRP at admission is 3.38 mg/L, which may be applicable to predict COVID-19 outcomes." (PMID 35126355, 2021). "Furthermore, despite including laboratory data obtained on the same day as the chest CT, we did not provide correlation analysis with biomarkers (e.g., interleukin-6, C-reactive protein, D-dimer, ferritin, etc.)known to be predictors of mortality in COVID-19." (PMID 34419163, 2021). "They found high concentrations of CRP in deceased patients and suggested that CRP could efficiently predict COVID-19 disease prognosis." (PMID 33727641, 2021). "Older age, male sex, obesity, hypertension, chronic pulmonary diseases, CVD, active cancer, laboratory parameters (e.g. low lymphocyte count, and elevations in CRP, ALT and AST) have been linked to a poor prognosis of COVID-19 in the general population infected with SARS-CoV-2." (PMID 33907860, 2021). "In addition, CRP is also an indicator for renal replacement therapy and the need for mechanical ventilation in COVID-19 patients." (PMID 33907513, 2021). "COVID-19’s ability to trigger pro-inflammatory cytokines such as C-reactive protein (CRP), ferritin, lactate dehydrogenase (LDH), D-dimer, IL-6, and IL-2 is known to activate a cytokine storm—an immune overreaction to viral particles that leads to organ damage." (PMID 34960687, 2021).
COVID-19 (continued). "In the inflammation process of COVID-19, CRP, platelet, ferritin, and leukocyte values may increase, while albumin and lymphocyte values may decrease." (PMID 33726485, 2021). "This may be attributable to the fact that COVID-19-positive patients had more severe disease and higher CRP level." (PMID 34190873, 2021). "Consistent with this hypothesis, levels of CRP, ferritin, IL-6, IL-8, and tumour necrosis factor alpha are significantly increased in deceased patients with COVID-19 compared to those who survived and are independent predictors of survival." (PMID 33824762, 2021). "Patients with obesity have higher concentrations of circulating tumor necrosis factor-alpha (TNF-a), interleukin-6, and C-reactive protein (CRP); this low grade chronic inflammatory state may be involved in initiating cytokine storms in patients with COVID-19." (PMID 34068824, 2021). "Patients with COVID-19 might show normal or lower leucocyte or lymphocyte counts, with increased CRP level." (PMID 33008329, 2020). "Moreover, we have demonstrated that inflammatory parameters, including SAA, PCT, CRP, hsCRP and IL-6 fluctuated with the deterioration of COVID-19." (PMID 33172355, 2020). "According to this dataset, patients with severe COVID-19 have a higher incidence of high CRP (81.5%, 110 cases out of 135) than those with a mild form of the disease (56.5%, 371 cases out of 658) suggesting an odds ratio (OR) of 3.4 with 95% confidence interval (95% CI) (2.15 to 5.4)." (PMID 32876941, 2020). "Furthermore, ROC Curve analysis revealed that the area under the curve (AUC) for CRP combined with lymphocyte proportion to diagnose severe events in fevered adult COVID-19 patients was 0.874 (95% CI 0.820–0.927)." (PMID 32719804, 2020). "In most patients with hematological malignancies COVID-19 mortality was directly driven by older age, disease status, performance status, as well as by immune (neutropenia) parameters and level of inflammation (high CRP)." (PMID 32864192, 2020). "The aim of the present study was to estimate whether the CRP level is able to act as a marker in indicating the severity of COVID-19." (PMID 32414383, 2020). "In this study, we retrospectively studied 419 patients from five hospitals in Shanghai, Hubei, and Jiangsu Provinces and determined several risk factors for the severity of COVID-19 in these patients, including age ≥60 years, ALB level, comorbidity, and CRP level." (PMID 33330318, 2020). "As for the laboratory results, the higher levels of ESR, CRP, UN, LDH, and HBDH were found in severe COVID-19 patients, suggesting that there is an association between disease progression and the injury of cellular immunity, cardiomyocytes, the liver, and the kidney." (PMID 32985562, 2020). "In common practice for urgent stratification, it is difficult to perform a large panel of biological analyses on admission but the routine test of CRP could predict disease severity and guide management of COVID-19 patients to different extents." (PMID 33312067, 2020). "In severe COVID-19 patients, CRP increased significantly before CT findings." (PMID 33363185, 2020). "This case underscores the potential importance of early serial measurements of IL-6 and cytokine storm-associated acute phase reactants, such as ferritin, D-dimer, and C-reactive protein, in guiding clinical decision-making in the management of patients with suspected COVID-19." (PMID 32635353, 2020). "The increase in the CRP levels further confirms the increased inflammatory conditions (hypercoagulability and activated platelets) in COVID-19 patients, as CRP is an acute marker of inflammation but, also, plays a role in the acute-phase immune response in the body." (PMID 33153161, 2020). "Despite the reduction in overall test volumes, a few tests e.g. Albumin, Troponin-I (Trop-I) and C - reactive protein (CRP) exhibited more than usual demands as they were being used for COVID-19 cases in supplementation to the molecular diagnosis and later for prognosis." (PMID 32551102, 2020).
COVID-19 (continued). "Anosmia, myalgia, fever and female sex were independent predictors of headache in hospitalized COVID-19 patients, while lower age and lower baseline disability, CRP, platelet value, lymphocyte count and D-dimer values on admission were independently associated with the presence of headache." (PMID 32727345, 2020). "Univariate analysis showed that erythrocyte count, hemoglobin level, neutrophil counts, LDH, procalcitonin, CRP, and IL-6 may be factors that affect the adverse clinical outcome of COVID-19." (PMID 33192519, 2020). "Dramatic drops in HRV correlated with subsequent spikes in CRP in COVID-19 patients." (PMID 33206183, 2020). "Creatine kinase levels might be increased above 200 U/L, increasing D-dimer, C-reactive protein (CRP), and lowered lymphocyte count if the skeletal muscle injury occurred despite of positive COVID-19 polymerase chain reaction test." (PMID 33169060, 2020). "Interestingly, two classical inflammation markers (ESR and CRP) in circulating blood were expressed oppositely in COVID-19 patients." (PMID 33282889, 2020). "In COVID-19, the exact effect of CRP remains unclear, but it was reported that their level can be used for early diagnosis of pneumonia, and assessment of severe pulmonary infectious diseases." (PMID 33312067, 2020). "Our findings support the utility of daily CRP values in hospitalized COVID-19 patients and provide early thresholds during hospitalization that may facilitate risk stratification and prognostication." (PMID 33216774, 2020). "Cox regression analysis including the parameters differed between patients with pneumonia and those without indicated that older age and circulating levels of IL-6, CRP, procalcitonin, and lactate at the 1st day after admission to hospital significantly predicted the progression of COVID-19." (PMID 33239109, 2020). "The test results could change quickly because of the progression of COVID-19, and as a consequence, we concerned the CRP, SAA, and blood routine as valid only for two days." (PMID 32724668, 2020). "Notably, both an increase in CRP and IL-6 and a decrease in lymphocytes were common in COVID-19 patient sera." (PMID 33195363, 2020). "Moreover, some studies evaluated the severity prediction of the COVID-19 using different factors such as age, gender, comorbidities, high neutrophil count, lymphopenia, high CRP level, and high lactate dehydrogenase level." (PMID 33312067, 2020). "Our findings also suggest lymphocyte count, creatinine and CRP concentrations might be significant predictors for the death of COVID-19 in these patients." (PMID 32641974, 2020). "Additionally, in mild COVID-19 patients, there were nine patients (41%) that had normal CRP content whereas SAA increased significantly above the normal range." (PMID 32713370, 2020). "In this case report we present a Caucasian patient with COVID-19 who developed a marked elevation of inflammatory parameters with ferritin 36,023 μg/L, but also elevated C-reactive protein 334 mg/L and lactate dehydrogenase 1074 U/L, 1 week after admission to the intensive care unit." (PMID 33054818, 2020). "Liver injury is associated with CRP-level; however, there is no predictor of liver injury in COVID-19 infected patients." (PMID 33425269, 2020). "With the following parameters such as age > 52 years, C-reactive protein > 64.79 mg/L, lactate dehydrogenase > 245 U/L, D-dimer > 0.96 μg/mL, serum amyloid A > 100.02 mg/L, or albumin < 36 g/L, the progress of COVID-19 to critical stage should be closely observed and possibly prevented." (PMID 32677918, 2020). "Clinically, increased CRP levels might be early indicators of nosocomial infections in COVID-19 patients who were slow to recover, and might aid physicians to administer empirical antibiotics treatment early to prevent worsened outcome." (PMID 32414383, 2020). "When compared to survivors, deceased COVID-19 had significantly higher medians of glycemia and CRP." (PMID 33425138, 2020).
COVID-19 (continued). "Some inflammatory (procalcitonin, CRP), haematologic (lymphocyte, Thrombocytes), and biochemical (CK-MB, Troponin I, D-dimer, ASAT, ALAT, LDH, γ-GT) biomarkers are significantly associated with severe COVID-19." (PMID 32879731, 2020). "A study in China on 21 patients with severe COVID-19 showed that TCZ causes absorption of pulmonary lesions in about 90.5% infected patients, while C‐reactive protein (CRP) values, body temperature, and the ratio of peripheral blood lymphocytes bring back to normal condition." (PMID 33178016, 2020). "At the early stage of COVID-19, CRP levels were positively correlated with lung lesions." (PMID 32588812, 2020). "In the moderate COVID-19 group, all patients had significantly higher levels of CRP and SAA." (PMID 32713370, 2020). "LDH, CRP and age can be used to identify severe patients with COVID-19 on hospital admission." (PMID 32746957, 2020). "The predictive role of CRP for severe COVID-19 has been previously reported." (PMID 33304910, 2020). "Combination of eosinopenia together with elevated high-sensitivity CRP could effectively triage suspected patients with COVID-19 from the other patients with fever." (PMID 32695683, 2020). "COVID-19 patients with moderate elevations of CRP levels (e.g., > 20–40 μg/mL) may harbor some level of (reversible) tissue damage associated with the natural response to combating the viral disease." (PMID 32588812, 2020). "Thus, for the OS of patients with COVID-19, the independent prognostic risk factors comprised CEA, WBC, CRP, PCT, Fer, D-dimer, Neu%, and L%." (PMID 33537326, 2020). "The presence of the most common headache symptoms in this sample (frontal or bilateral diffuse pain, intense pain, pressing pain, and hypersensitivity to stimuli) was related to the laboratory biomarkers of severe COVID-19 state, i.e., lymphopenia and high values of CRP and PCT." (PMID 33391152, 2020). "C-reactive protein that is measured in plasma (including that measured in COVID-19 patients) is a very soluble, non-covalently associated cyclic pentameric protein that has weak anti-inflammatory bioactivities." (PMID 32588812, 2020). "In COVID-19 patients, elevated plasma CRP levels are a prognostic indicator of adverse outcomes." (PMID 32922297, 2020). "Critically ill COVID-19 patients exhibited an increased ratio of white blood cells/lymphocytes and higher plasma levels of C-reactive protein (CRP), IL-2, IL-7, IL-10, GSCF, IP10 (CXCL10), MCP-1 (CCL2), MIP-1α (CCL3), and TNF-α, as compared to non-ICU patients." (PMID 32998763, 2020). "Additionally, COVID-19 patients on intensive care unit (ICU) often develop a hyperinflammatory response with high levels of C-reactive protein (CRP) and excessive production of inflammatory cytokines." (PMID 33198670, 2020). "CRP and lymphocyte have been confirmed as prognostic biomarkers since the outbreak of COVID-19 and they were also recommended as the early warning indicators for severe and critically ill cases by Chinese Clinical Guidance for COVID-19 Pneumonia Diagnosis and Treatment (7th edition)." (PMID 32922185, 2020). "We performed a multivariate logistic analysis and found that BMI, hypertension and CRP were dependent risk factors for the severity of COVID-19, while serum ACE activity was not." (PMID 33238910, 2020). "In 30 personally encountered consecutively hospitalized patients with qPCR-proven COVID-19 studied initially as a pilot cohort, we found that elevated C-reactive protein (CRP) and lactate dehydrogenase (LDH) levels as well as lymphocytopenia were characteristic laboratory patterns." (PMID 32828735, 2020). "Elevations in CRP appear to be unique to COVID-19 patients when compared to other viral infections." (PMID 33147871, 2020).